RUNX2 (RUNX family transcription factor 2)
Diseases named in the same sentence as RUNX2 in open-access papers (continued):
Sharing a sentence is not in itself a finding about the gene and the disease.
cancer (continued). "Recent studies aimed at targeting the transcriptional component of cancer development have yielded a small molecule inhibitor of Runx2, CADD522." (PMID 34503118, 2021). "Runx2 is primarily responsible for regulating skeletal development and has been observed to be aberrantly expressed in several cancers which metastasize to the bone including breast, prostate, and lung." (PMID 34503118, 2021). "The analysis of 942 cases of cancer tissues revealed a significant positive correlation among RUNX2, BRG1, and CD44." (PMID 33071648, 2020). "The prominent role of SOX9 and RUNX2 in the normal development of ectodermal and mesodermal originated tissues makes them particularly prone to being hijacked by cancer cells and exploited during neoplastic initiation, development, and progression." (PMID 33287223, 2020). "In low-metastatic potential MCF-7 cells, high levels of RUNX2 significantly enhanced cancer invasiveness." (PMID 32139701, 2020). "Runt-related transcription factor-2 (RUNX2) is a mesenchymal stem marker for cancer that is involved in stem cell biology and tumorigenesis." (PMID 33071648, 2020). "Runx2 was involved in osteoblastic differentiation, skeletal morphogenesis and cancer progression 23-25." (PMID 32913476, 2020). "ID1, ID2 and RUNX2 were also shown to conduce to cancer cell invasiveness, and BAMBI is a BMP target gene implicated in CRC metastasis." (PMID 32326239, 2020). "RUNX2 functions as a key transcription factor in osteoblastogenesis and is highly expressed in cancers as well as human tissue microarrays in both adenocarcinoma and metastasis." (PMID 33062960, 2020). "As a mesenchymal stem marker for cancer, RUNX2 is involved in stem cell biology and tumorigenesis, and, possibly, in the regulation of CSC." (PMID 33071648, 2020). "Taken together these data indicate that HDAC1, binding to the RUNX2 P2 promoter, prompts RUNX2 expression in cancer cells." (PMID 31395086, 2019). "An increase in the expression of OPN and MMP-9 suggest that RUNX2 contributes to the metastatic property of cancer cells." (PMID 31331331, 2019). "RUNX2 is discovered as a master regulator of osteogenesis, but is abnormally expressed in several cancer types, including NSCLC." (PMID 31832019, 2019). "RUNX2 is not an exception to this paradigm but the mechanisms leading to RUNX2 expression in cancer remained unclear for long time." (PMID 31395086, 2019). "TPC1 cells display significantly higher levels of RUNX2 compared to the rest of tested cancer cell lines, including MDA-MB231." (PMID 31395086, 2019). "Proliferation assays and evaluation of RUNX2 mRNA levels by qRT-PCR were used to evaluate the effect of several HDACi and specific siRNAs on a panel of cancer cell lines." (PMID 31395086, 2019). "In conclusion, HOXA9, a positive regulator of RUNX2, can enhance calcification and cancer migration and invasion ability in PTC, dependent and independent of RUNX2." (PMID 31043660, 2019). "Among the different cancer cell lines tested, this double activity of HDACs on RUNX2 seemed specific for TPC1." (PMID 31395086, 2019). "RUNX2 was also known as a cancer-related transcription factor to promote the adhesion of endothelial pulmonary cells and the cancer lung metastasis." (PMID 31832019, 2019). "In particular, we provided additional details on the molecular mechanisms that drive RUNX2 aberrant expression in cancer and strengthen the rationale for the use of HDACi as potential therapeutic strategy to counteract the oncogenic program driven by RUNX2." (PMID 31395086, 2019). "Previously, we showed that suppressing the activity of the epigenetic regulators HDACs significantly represses RUNX2 expression highlighting a role for these enzymes in RUNX2 reactivation in cancer." (PMID 31395086, 2019).
cancer (continued). "In line with this non-canonical function, here we reported that HDACs are necessary to sustain the expression of RUNX2 in cancer cells and that treatment with HDACi inhibits this TF leading to a concomitant growth inhibition." (PMID 31395086, 2019). "To clarify this discrepancy, we recently identified three intergenic ENHs (ENH3, ENH11 and ENH13) that, brought together by chromatin tridimensional looping, cooperate to enhance and regulate RUNX2 transcription in cancer." (PMID 31395086, 2019). "In this work we aimed to explore the way HDACs control the expression of RUNX2 in cancer cells pointing at clarifying which HDACs are involved and their mechanisms of action." (PMID 31395086, 2019). "To further explore the cooperation of RUNX2 and HDAC6 in inducing transcription of cancer related genes, we investigated their binding on the promoters of a selected set of genes identified as commonly repressed upon RUNX2 and HDAC6 silencing." (PMID 31395086, 2019). "In this study, we showed that Class I HDACs and in particular HDAC1 are required for RUNX2 efficient transcription in cancer." (PMID 31395086, 2019). "Among the identified HDAC6-RUNX2 target genes we found SPP1, a consolidated RUNX2 target involved in cancer cells migration and invasiveness." (PMID 31395086, 2019). "We recently reported that HDACi inhibits RUNX2 expression in several cancer types and that the strength of this inhibition is tightly dependent on RUNX2 levels of expression." (PMID 31395086, 2019). "Several reports have demonstrated that the activation of Runx-2 is related to cancer progression and metastasis." (PMID 30105080, 2018). "Runx-2 is being increasingly recognized as regulating the development of cancer and its progression." (PMID 30105080, 2018). "A significant group effect was observed on the number of RUNX2-positive cancer cells (p=0.0187), after which post hoc testing showed significantly in BM− (375.4 ± 20.97) respect to BL (273.3 ± 27.14) (p=0.0006)." (PMID 30627063, 2018). "It has been reported that RUNX2 is a negative regulator of pRB (retinoblastoma protein), which has been demonstrated as a cell cycle inhibitor, thus promoting the cancer cell proliferation." (PMID 28938538, 2017). "With RUNX2 identified as a potentially useful therapeutic target against cancer angiogenesis, we believe our findings will contribute to cancer therapy development." (PMID 28938538, 2017). "This discovery addresses a novel function of RUNX2 and an innovative direction for treatment of anti-angiogenesis in cancer therapy." (PMID 28938538, 2017). "The hOC promoter is activated by transcription factors such as Runx2 and Fra-2, which are commonly overexpressed in cancers that metastasize to bone." (PMID 28325291, 2017). "Recent studies have found that Runx2 is overexpressed in cancer cells, enhancing their migration and invasion." (PMID 28264434, 2017). "The molecular basis for RUNX2 as an oncogene in cancer has been studied in several malignant tumors." (PMID 27007162, 2016). "RUNX2 further affects cancer cell invasion and osteolysis, which seems also true for ES as demonstrated by us in the context of DKK2." (PMID 27363011, 2016). "Recently, the involvement of Runt-related transcription factor 2 (RUNX2) in cancer development has been increasingly recognized." (PMID 27007162, 2016). "The functional elucidations of RUNX2 transcriptional targets would significantly improve the understanding of the propensity of certain cancers to metastasize to the skeleton." (PMID 27806311, 2016).
cancer (continued). "Mechanistic studies mainly performed in osteoblasts and chondrocytes and in different cancer cellular systems shed light into a functional interaction and cooperation between RUNX2 and the PI3K/AKT pathway." (PMID 26204939, 2015). "Several lines of evidence indicate that the dysregulation of RUNX2 expression is frequently detectable in a variety of human cancers and its higher expression level is tightly correlated with poor clinical outcome of the patients." (PMID 26512706, 2015). "Previous studies have indicated that Runx2 can regulate aspects of mammary cell function and influence the properties of cancer cells." (PMID 26489514, 2015). "It was also reported that imatinib, a tyrosine kinase inhibitor used for BCR/ABL1-positive cancers treatment, upregulated RUNX2 expression in human mesenchymal stem cells (hMSCs) at early differentiation stages." (PMID 26404249, 2015). "In fact, RUNX2 influence several genes involved in cancer cells metastasis and invasion, such as BSP, MMPs (Matrix Metalloproteinases), or VEGF." (PMID 26404249, 2015). "RUNX2 is a transcription factor playing the major role in osteogenesis, but it can be involved in DNA damage response, which is crucial for cancer transformation." (PMID 26404249, 2015). "Surprisingly, in that study, the subset of cancer cells showed nuclear staining for RUNX2 correlated with ER, suggesting that in those cells both RUNX2 and estrogen receptor acted synergistically, stimulating cancer development." (PMID 26404249, 2015). "RUNX2 is also elevated in many other cancers, such as breast and prostate cancers, gliomas, and it was also correlated with bone metastasis." (PMID 26404249, 2015). "COL10A1 is not expressed in normal colon epithelium, but is a direct transcriptional target of RUNX2, a transcription factor that is expressed in cancer cells, and has been related to multiple cancers." (PMID 25215506, 2014). "In this study, we find that Runx2 suppression robustly enhances apoptotic cell death in invasive cancer cell lines in response to glucose- and growth factor-deprivation." (PMID 24479521, 2014). "Transcriptional regulation of TSP-1 in osteogenesis and cancer is poorly understood; this prompted us to study its regulation by the two key regulators of the processes: Runx2 and Runx3." (PMID 23846726, 2013). "In a sharp contrast to RUNX1 and RUNX3, oncogenic property of RUNX2 has been postulated in several human cancers." (PMID 24078903, 2013). "In cancer cells, Runx2 activates cancer-related genes, promotes cells invasive properties, cooperates with oncogenes (e.g., c-myc in T-cell lymphoma development), and suppresses apoptotic and growth arrest pathways." (PMID 22537242, 2012). "RUNX2 has potential to be predictive of response to the standard chemotherapy regimen according to studies by our lab, but further work to discover its cancer-specific function is needed." (PMID 21197465, 2011). "In T-cell lymphomas, overexpression of RUNX2 and the MYC oncogene leads to cooperation between the encoded proteins that maintains survival and proliferation in the cancer cells." (PMID 21197465, 2011). "In bone metastatic breast cancer, RUNX2 promotes cancer cell survival and growth by activating expression of IHH and interacts with the TGFβ/BMP signal transduction pathway to parathyroid hormone-related protein (PTHrP)." (PMID 20465837, 2010). "RUNX2 is normally expressed in lineage-committed mesenchymal progenitor cells with a osteogenic cell fate, but RUNX2 expression is also aberrantly induced in different cancer cell types." (PMID 21029421, 2010). "Current evidence indicates that RUNX2 is a key pathological factor in metastatic breast, prostate and bone cancer cells, as well as in lymphomas in mouse models." (PMID 21029421, 2010). "The regulation of SPHK1 by Runx2 probably potentiates additional aspects of the cancer phenotype, including angiogenesis (a function assisted by the Runx2 targets VEGFA and EDN2) and drug resistance." (PMID 20863401, 2010).
cancer (continued). "One of the most pivotal regulators is Runx2 (Runt-related transcription factor 2), a lineage-specific transcription factor essential for osteogenesis and increasingly recognized for its role in cancer metastasis." (PMID 41596432, 2026). "TEX41 has also been studied in the context of cancer where it may play a role in regulating autophagy by increasing Runx2 levels, and may control cancer cell proliferation and migration by regulating miR153-3p levels." (PMID 41602168, 2026). "Our data indicate that RUNX2 – through its widespread transcriptional activity – is a key factor for a balanced gene expression that fosters cancer cell fitness through the downregulation of mitochondrial respiration and the promotion of anabolic pathways like de novo lipogenesis." (PMID 41174748, 2025). "RUNX2 is overexpressed in various cancers, including breast (BC) and thyroid cancer (TC), where it promotes metastasis by regulating key functions such as stress resistance and phenotypic plasticity through processes like the Epithelial-to-Mesenchymal Transition (EMT) and osteomimicry." (PMID 41174748, 2025). "Its expression in high-grade EWS and OS may be related to the upregulation of RUNX2 which induces cancer cell proliferation." (PMID 41374993, 2025). "A recent study revealed that RUNX2 affects cancer metabolism inducing plasticity and metastasis." (PMID 41511334, 2025). "In addition, our data revealed that besides RUNX2, RAIN governs a hierarchically organized complex transcriptional program by controlling a core of cancer-associated TFs that, in turn, orchestrate the expression of downstream genes." (PMID 39271656, 2024). "The RUNX family, consisting of RUNX1, RUNX2, and RUNX3, has been recognized as crucial regulators in developmental processes, with dysregulation of these genes also being implicated in tumorigenesis and cancer progression." (PMID 39822248, 2024). "RUNX2 contributes to the chemo-resistant phenotype in several cancers." (PMID 38430423, 2024). "In the context of chondrosarcoma, RUNX2 may promote cancer progression by regulating genes involved in cell proliferation, invasion, and angiogenesis." (PMID 38542153, 2024). "Data indicate that Runx2 may play a critical role in the development of malignant tumors, metastasis, angiogenesis, proliferation, and resistance to antitumor drugs." (PMID 39595568, 2024). "In addition to RUNX2, RAIN directly controls other cancer-associated TFs, that in turn propagate its regulatory function by modulating the expression of other downstream genes." (PMID 39271656, 2024). "RUNX2 is a transcription factor that participates in osteoblast differentiation and chondrocyte maturation and plays an important role in the invasion and metastasis of cancers." (PMID 36897488, 2023). "We can speculate that in cancer, the expression level of the RUNX2 TF is higher in less differentiated cells, and therefore, in cells with metastatic properties." (PMID 37754231, 2023). "Knockdown of RUNX2 diminished the proliferation rate of cancer cells." (PMID 37108164, 2023). "Additionally, studies indicated that BRD4 is a known trigger of Runt-related transcription factor 2 (RUNX2), and in some cancer cells, RUNX2 is a direct target of BRD4 inhibition by JQ-1." (PMID 37509171, 2023). "P‐MAPK11 could have physical interaction with RUNX2, and hence promote cell proliferation and migration in the cancer in question." (PMID 37525479, 2023). "RUNX2 appears to be a prognostic biomarker in many cancer types." (PMID 37108164, 2023). "Recent research has uncovered numerous somatic mutations in the RUNX2 gene in various cancers, including missense, nonsense, and nonstop mutations and frameshift insertions and deletions." (PMID 37759525, 2023). "RUNX2 RNA and protein expression levels in various types of cancer were measured." (PMID 37108164, 2023).
cancer (continued). "Runt-related transcription factor-2 (Runx2), although initially defined as a transcription factor responsible for osteogenic differentiation in mammals, is closely related to proliferation, invasion, and bone metastasis of multiple cancer types." (PMID 38258065, 2023). "In contrast to RUNX1 and RUNX3, which may function as oncogenes or tumor suppressors, RUNX2 is mostly overexpressed and oncogenic in human cancer." (PMID 37190015, 2023). "Although our lab’s results suggest RUNX2 may be predictive of responses to regular chemotherapy, further research is required to determine its cancer-specific role." (PMID 37370857, 2023). "The role of RUNX2 in cancers has been explored in many studies." (PMID 36897488, 2023). "We demonstrated that CUL4B is a new regulator of RUNX2 for osteogenic differentiation in PDLSCs, but the relationship between CUL4B and RUNX2 in cancers remains unknown." (PMID 35784474, 2022). "Instead, we not only verified the tumorigenic role of RUNX2 in TNBC progression and cancer chemoresistance both in vitro and in vivo, but also revealed the regulatory mechanism of RUNX2 via directly targeting the specific binding site in the promoter region of MMP1." (PMID 36483054, 2022). "Thus, both TRβ1 and Runx2 are regulated by calcium signals, and by overexpressing TRβ1 the cancer cells obtained a more normal thyroid cell phenotype." (PMID 36497320, 2022). "Somatic mutations in RUNX2 and RUNX3 are rare in different cancers." (PMID 36429115, 2022). "Notably, we observed that silencing CBFB in MDA-MB-436 cells resulted in the reduced expression of EMT regulator Snail, metastasis/cancer stem cell marker CD44, and bone metastasis–associated markers OPN and Runx2." (PMID 35903297, 2022). "RUNX2 had higher expression in 12 types of cancer and low expression in one type." (PMID 35522574, 2022). "Therefore, further investigations are needed to characterize the mutual interactions of CUL4B and RUNX2 in cancers including miR-320c2 and miR-372-3p/373-3p." (PMID 35784474, 2022). "The major function of RUNX2 in the context of cancer is to promote cancer metastasis." (PMID 36429115, 2022). "RUNX2 alters nutrient metabolism including glucose metabolism in cancers." (PMID 35665333, 2022). "It is suggested that RUNX2 might play a critical role in building a bone microenvironment to facilitate cancer cell to bone, however, the molecular mechanism needs to be further investigated." (PMID 35534547, 2022). "The differences in the expression of miR-218-5p and RUNX2 between cancer cell lines may be related to the specific characteristics of each type." (PMID 35805994, 2022). "In addition, RUNX2 is upregulated under hypoxic stress conditions in cancer cells, resulting in increased expression of the anti-apoptotic gene Bcl-2." (PMID 36231060, 2022). "The results indicated that RUNX2 expression was significantly upregulated in these carcinomas." (PMID 35534547, 2022). "The present study suggests that RUNX2-mediated MMP13 expression controlled by ABL may lie downstream of not only cancer biology but also other physiologic pathways." (PMID 34136397, 2021). "WWP1 contains two WW domains that have been shown to recruit and modulate the activity of cancer related proteins like Runt-related transcription factor 2 (RUNX2), RING finger protein 11 (RNF11) and large tumor suppressor kinase 1 (LATS1) via their proline-rich (PY) motifs." (PMID 33869064, 2021). "Many upregulated genes such as cancer stem cell marker (SOX2/9), hypoxia inducible factor (HIF1α), TGF-β signaling associated receptor (TGFBR2), and differentiation related transcription factor (RUNX2) were reported to promote tamoxifen resistance." (PMID 32420379, 2020).